GBP5 (guanylate binding protein 5)
Diseases named in the same sentence as GBP5 in open-access papers (continued):
Sharing a sentence is not in itself a finding about the gene and the disease.
ovarian carcinoma (7 papers, 2021 to 2025). A malignant neoplasm originating from the surface ovarian epithelium. "We observed that GBP5, the most significantly different gene in the low-risk group, holds significant implications for ovarian cancer." (PMID 40225866, 2025). "Ovarian cancer organoids have also been employed to study the immunoreactive microenvironment and the role of guanylate-binding protein 5 (GBP5) in suppressing cancer progression through canonical pyroptosis." (PMID 40427552, 2025). "Subsequently, we found that early-stage (Stage I-II) OC patients exhibited significantly higher GBP5 expression levels compared to those with late-stage (Stage III-IV) ovarian cancer." (PMID 40225866, 2025). "After 48 hours of induction with three drugs, flow cytometry analysis showed that knocking down GBP5 reduced the percentage of apoptotic cells in the HEYA8 ovarian cancer cell line." (PMID 40225866, 2025). "To further elucidate the impact of GBP5 on ovarian cancer phenotypes, we evaluated cell viability using the CCK8 assay." (PMID 40225866, 2025). "In this study, we identified a pyroptosis-related protective factor, GBP5, which significantly inhibits the growth of ovarian cancer cells and patient-derived ovarian cancer organoids, impeding the invasion and migration of ovarian cancer cells." (PMID 38817865, 2024). "External immunotherapy database analysis showed profound potential for the application of GBP5 in immunotherapy strategies for ovarian cancer." (PMID 38817865, 2024). "Overall, our study demonstrates that the protective factor GBP5 significantly inhibits ovarian cancer progression, triggering canonical pyroptosis through the JAK2-STAT1 pathway." (PMID 38817865, 2024). "Further research confirmed that GBP5 in ovarian cancer cell can induce canonical pyroptosis through JAK2/STAT1 pathway, thereby restraining the progression of ovarian cancer." (PMID 38817865, 2024). "In colony formation assays, both GBP5 knockdown cell lines demonstrated an increase in the number and volume of colonies formed compared to the control group (P<0.05), suggesting that GBP5 plays a role in suppressing ovarian cancer cell proliferation." (PMID 40225866, 2025). "Furthermore, we have verified the function of GBP5 in OC through cellular experiments and its impact on chemotherapy sensitivity after altering GBP5 expression in ovarian cancer cells." (PMID 40225866, 2025). "Similarly, in ovarian cancer, organoid models have been crucial in identifying GBP5 as a key factor in pyroptosis, a form of RCD that can inhibit tumor progression." (PMID 40427552, 2025). "Interestingly, in this study, we also discovered that ovarian cancer cells with high GBP5 expression exhibit increased expressions of CXCL9/10/11 in a co-culture assay." (PMID 38817865, 2024). "GBP1 binds to proto-oncogene serine/threonine-protein kinase pim-1 (PIM1) and causes paclitaxel resistance in ovarian cancer, implying that PIM1 might interact with GBP5 for drug resistance in OSCC." (PMID 34439200, 2021). "We assessed GBP5 expression across several ovarian cancer cell lines compared to the normal ovarian epithelial cell line IOSE80 using RT-qPCR, revealing that GBP5 is relatively upregulated in the SKOV3 and HEYA8 cell lines." (PMID 40225866, 2025). "Based on patient-derived ovarian cancer organoid (PDOCO) model, we observed that GBP5 potentially impeded OC growth at organ level." (PMID 38817865, 2024).
colorectal cancer (6 papers, 2021 to 2025). A primary or metastatic malignant neoplasm that affects the colon or rectum. "In addition to colorectal cancer, GBP5 is also associated with coronavirus disease COVID-19 and Pathogenic Escherichia coli infection, indicating that GBP5 may play a role in other diseases." (PMID 36246628, 2022). "Similar, the association of high-expression with positive patient outcome has been previously reported for GBP5 in other cancer types such as skin, breast and colorectal cancer." (PMID 34062972, 2021). "In addition, M1 macrophages, which are considered antineoplastic, became more numerous in the BTZ-treated shB-Myb colorectal cancer cells–bearing mice, as evidenced by the increased CD11b/iNOS and CD11b/GBP5 double-positive cells, which was quantified." (PMID 38565963, 2024). "As expected, the expression levels of iNOS and GBP5, which are biomarkers of M1 macrophages, were upregulated in response to the conditional medium from BTZ-treated shB-Myb colorectal cancer cells." (PMID 38565963, 2024). "However, the role of GBP5 in pan-cancer, including colorectal cancer (CRC), remains unclear." (PMID 36246628, 2022).
gastric cancer (6 papers, 2018 to 2025). A primary or metastatic malignant neoplasm involving the stomach. "In oncology, GBP5 has been implicated in promoting the proliferation and migration of gastric cancer (GC) cells, and modulating immune interactions within the glioma microenvironment, contributing to tumor progression." (PMID 40788157, 2025). "ROC analysis identified genes with high specificity and sensitivity for discriminating EBV+ gastric cancer, including GBP5, CMKLR1, GM2A and CXCL11 that play pivotal roles in immune response, inflammation, and cancer." (PMID 40110195, 2025). "In gastric cancer, positive correlation between immune cell infiltration and stromal and epithelial GBP5 expression has been reported." (PMID 30333036, 2018).
HIV-1 infection (6 papers, 2017 to 2024). The type species of lentivirus and the etiologic agent of acquired immunodeficiency syndrome (AIDS). "For example, HIV-1 infection activates LTR12C elements upstream of the interferon-inducible genes GBP2 and GBP5 that encode for broad-spectrum antiviral factors." (PMID 33021676, 2020). "The guanylate binding protein 5 (GBP5) has very recently been discovered as a new restriction factor of HIV-1 infection, that interferes with viral Env proteins, thereby decreasing infectivity of produced virions." (PMID 29088112, 2017). "However, upon HIV-1 infection, GBP5 co-localizes with HIV-1 and reduces the production of infectious HIV-1 particles." (PMID 39221250, 2024). "We would also like to point out that HIV-1 infection resulted in a more pronounced activation of the LTR12C repeat upstream of GBP2 (∼8-fold increase) in comparison to the LTR12C element upstream of GBP5 (∼2-fold increase), and only the former reached statistical significance." (PMID 33021676, 2020). "Combining an unbiased RNA-sequencing approach with mechanistic analyses, we demonstrate that these solo-LTRs harbor transcription start sites that are activated upon HIV-1 infection and govern the expression of GBP2 and GBP5." (PMID 33021676, 2020). "Similarly, GBP2 and GBP5 are two guanylate binding proteins known to restrict HIV-1 entry and previously shown to be transcribed from LTR12C elements upon HIV-1 infection of primary CD4+ T cells." (PMID 38168352, 2023). "HIV-1 infection results in the upregulation of several LTR12C elements, which act as promoters for the interferon-inducible guanylate-binding proteins 2 (GBP2) and 5 (GBP5)." (PMID 35891571, 2022). "Notably, HIV-1 infection induced the expression of IFN-γ in our RNA-seq study, suggesting that HIV-1 may at least in part activate LTR12C-driven GBP2 and GBP5 expression via an increased release of IFN-γ." (PMID 33021676, 2020).
melanoma (6 papers, 2013 to 2024). A malignant, usually aggressive tumor composed of atypical, neoplastic melanocytes. "Finally, through our IHC experiments using tissue microarrays containing 17 cases of melanoma and 18 cases of normal skin tissues, we confirmed that GBP5 exhibited significantly higher expression levels in melanoma tumor tissues compared to normal tissues." (PMID 39355255, 2024). "Importantly, the expression levels of GBP5 showed a significant positive correlation with CD8+ T cell infiltration levels, corroborating our findings that ITRGM, which includes seven model genes, notably GBP5, is a promising biomarker for immunotherapy in melanoma." (PMID 39355255, 2024). "The ITRGM signature includes GBP5, HLA-DPB1, XBP1, CD40, CXCL10, and TNFSF13B, each playing pivotal roles in the immune response and tumor microenvironment of melanoma." (PMID 39355255, 2024). "Within the cytokine signaling pathway, GBP5 and KPNA2 have known roles in the immunomodulation and progression of melanoma, respectively." (PMID 35008167, 2021). "While there is currently no information on GBP5 in immunotherapy datasets of OC patients, data from research on melanoma patients receiving anti-PD-1 monotherapy is available." (PMID 38817865, 2024).
colitis (5 papers, 2024 to 2025). Inflammation of the colon. "Suppression of GBP5 mitigates colitis symptoms, and GBP5-deficient mice exhibit altered gut microbiota, increasing probiotic populations and potentially preserving intestinal immune balance." (PMID 40788157, 2025). "Strikingly, GBP5-deficient mice are resistant to dextran sulfate sodium (DSS)-induced colitis, further corroborating the role of GBP5 in gut inflammation." (PMID 41194916, 2025). "In colitis, GBP5 is closely linked to the composition and activity of the intestinal microbiota, emphasizing its critical role in maintaining gut immune balance." (PMID 40788157, 2025). "Here the authors profile transcriptional changes in humans after FMT and how this relates to colitis remission identifying a role for GBP5, and this protein is validated in a loss-of-function mouse model." (PMID 38531874, 2024). "Next, differences in Gbp5–/– mice that may be mechanistically associated with increased resistance to colitis were explored." (PMID 38531874, 2024). "In addition, the loss of Gbp5 mitigated colitis compared with its severity in the WT littermate controls, with a significantly decreased histological score, macroscopic score, and microscopic score." (PMID 39062588, 2024). "This decrease was not significant (p = 0.065) in the proximal colon where no signs of colitis were detected, indicating that claudin 2 levels were associated with histological detection of colitis, and that they may be key to colitis resistance in Gbp5–/– mice." (PMID 38531874, 2024). "Female mice with a deletion of GBP5 are more resistant to developing colitis than their wild-type littermates, showing higher colonic IRF4 phosphorylation." (PMID 38531874, 2024). "In support, we found that genetic deletion of GBP5 protected mice from colitis when they were compared to their wild-type littermates, and additionally IRF4 phosphorylation was dysregulated in their colonic tissue." (PMID 38531874, 2024). "Wildtype (WT) and Gbp5 knockout mice (Gbp5−/−) were repetitively treated with DSS (control mice drinking clean water) for 9 weeks to generate experimental chronic colitis." (PMID 39062588, 2024). "The major limitation of this study is that although we have found that GBP5 can promote the occurrence and development of colonic inflammation in vivo, the specific mechanism of how GBP5 exacerbates the immune response has not been fully determined." (PMID 39062588, 2024). "The colonic mucosal response discriminates UC remission following FMT, with GBP5 playing a detrimental role in colitis." (PMID 38531874, 2024). "The GBP5 appears to be a key modulator of colitis in humans and mice." (PMID 38531874, 2024). "Our collective findings would suggest that the concerted role of GBP5 and IRF4 extends beyond the response to FMT to a larger role in the development of colitis; however, further studies are required to confirm this." (PMID 38531874, 2024). "In the current study, we found HDAC3 promoting IFN-γ induced expression of GBP5, which in turn, potentiated the activation of NLRP3 inflammasomes and aggravated the disease severity of DSS-induced colitis." (PMID 38903915, 2024). "The results identify a role for GBP5, and potentially IRF4, in the establishment of colitis in mice." (PMID 38531874, 2024). "Mechanically, the current study revealed that HDAC3 promotes the development of colitis in macrophages by positively regulating IFN-γ-induced expression of GBP5 and enhancing the activation of NLRP3 inflammasomes in GBP5-dependent manners." (PMID 38903915, 2024). "Inflammatory factors such IFN-γ, TNF-α, and IL-1β can induce the expression of GBP5; these cytokines are highly expressed in IBD and in the experimental mouse models of colitis." (PMID 39062588, 2024).
colitis (continued). "Genetic deletion of GBP5 in mice showed that mice without GBP5 were more resistant to developing colitis than wild-type littermates, with concomitant regulation of IRF4 phosphorylation and the tight junction marker claudin 2 in their colonic tissue." (PMID 38531874, 2024).
diabetic cardiomyopathy (5 papers, 2021 to 2025). Diabetic cardiomyopathy is a disorder of the heart muscle in people with diabetes. "Another gene, encoding Glycoprotein Hormone Beta 5 (GBP5) is an inflammasome protein regulator that is implicated in caspase-1 dependent cell death and pyroptosis in diabetic cardiomyopathy." (PMID 37019881, 2023). "Here, we report inflammation-induced cell death mediated by inflammatory cells (macrophage and dendritic cells) and inflammasome formation (TLR4, NLRP3) and NLRP3 activators (Nek7 and GBP5) that cause cardiac cell death is the key player in the development and progression of diabetic cardiomyopathy." (PMID 34685620, 2021). "Additionally, BMP7 alleviates pyroptosis and inflammation and improves cardiac dysfunction in diabetic cardiomyopathy by inhibiting the Nek7/GBP5 signaling axis, thus suppressing inflammasome formation in cardiomyocytes." (PMID 40636987, 2025). "In the context of diabetic cardiomyopathy, bone morphogenetic protein-7 (BMP-7) alleviated inflammation-induced pyroptosis by inhibiting the TLR4-NLRP3 complex, which is activated by GBP5 and NIMA-related kinase 7 (Nek7)." (PMID 40788157, 2025). "The exact role of Nek7 and GBP5 in the heart as well as in diabetic cardiomyopathy has never been examined as per the best of our knowledge." (PMID 34685620, 2021). "Interestingly, treatment with BMP-7 attenuated the increased expression of Nek7 (p = 0.038) and GBP5 (p = 0.01) compared to the diabetic group, suggesting that BMP-7 attenuates inflammasome protein regulators Nek7 and GBP5 prior to the initiation of NLRP3 upregulation in diabetic cardiomyopathy." (PMID 34685620, 2021).
inflammatory bowel disease (5 papers, 2022 to 2025). A spectrum of small and large bowel inflammatory diseases of unknown etiology. "Besides IM-associated liver injury, the mechanism of GBP5 in activating the NLRP3 inflammasome plays a key role in the pathogenesis of inflammatory bowel diseases and arthritis." (PMID 40075517, 2025). "Based on KEGG enrichment, we also discovered that the gene sets related to cytokine-cytokine receptor interaction, inflammatory bowel disease, rheumatoid arthritis, and the IL-17 signaling pathway were downregulated in Gbp5−/− mice." (PMID 39062588, 2024). "In inflammatory bowel disease (IBD), GBP5 influences intestinal immunity and alters gut microbiota composition, further demonstrating its role in host-microbe interactions." (PMID 40788157, 2025). "Guanylate binding protein 5 (GBP5) is an emerging immune component that has been increasingly recognized for its involvement in autoimmune diseases, particularly inflammatory bowel disease (IBD)." (PMID 39062588, 2024).
oral squamous cell carcinoma (5 papers, 2020 to 2024). "However, the role played by GBP5 in cancer development, especially in oral squamous cell carcinoma (OSCC), is still unknown." (PMID 34439200, 2021).
COVID-19 (4 papers, 2022 to 2025). A disease caused by infection with severe acute respiratory syndrome coronavirus 2. "GBP genes were also upregulated in SARS-CoV-2-infected human alveolar epithelial type-2 (AT2) organoids and lung tissues from COVID-19 patients, with GBP5 being highly upregulated in both cases (~44 fold and ~16 fold vs mock-infected cells and normal lung tissue, respectively)." (PMID 41247044, 2025). "The optimal 2-gene signatures combine an interferon-stimulated gene (ISG) that is strongly induced in COVID-19, such as IFI6, with another immune response gene that is more strongly induced in other viral ARIs, such as GBP5." (PMID 36507688, 2023). "We therefore measured the expression of IFI6 and GBP5 (relative to the reference gene RPP30) using qPCR assays on swabs from a new cohort of patients with (n = 72) or without (n = 72) COVID-19 (Data Set S3)." (PMID 36507688, 2023).
gastric adenocarcinoma (4 papers, 2020 to 2021). "GBP5 is expressed highly in gastric adenocarcinomas as an immune modulator." (PMID 34439200, 2021). "Besides, the GBP5 gene has been studied in a variety of cancers, including gastric adenocarcinoma, skin cutaneous melanoma, pancreatic adenocarcinoma, and HCC, and GBP5 was one of the key genes in the malignant transformation induced by microcystin-LR (MC-LR) in the cell of HCC." (PMID 33897701, 2021).
glioma (4 papers, 2018 to 2024). A benign or malignant brain and spinal cord tumor that arises from glial cells (astrocytes, oligodendrocytes, ependymal cells). "We also examined the protein levels of GBP5 in a collection of 12 glioma cell lines." (PMID 33608513, 2021). "In addition, GBP5 is positively correlated with PD-L1 expression in human glioma, endowing it the role of a complementary prognostic indicator for anti-PD-1/PD-L1 therapy." (PMID 33608513, 2021). "Moreover, the expression of Cd274 was well correlated with the respective expression of Ifng, Irf1, Gbp5, and Ccl2, demonstrating that selected IFN-γ-induced genes serve as feasible substitute indicators for IFN-γ level and thus might synergistically indicate the prognosis of glioma." (PMID 30333036, 2018).
hepatocellular carcinoma (4 papers, 2021 to 2022). A malignant tumor that arises from hepatocytes. "GBP5 was identified as a prognostic gene in the TME of hepatocellular carcinoma and gastrointestinal stromal tumors." (PMID 35222540, 2022). "Src and ERK have been reported to participate in the MMP3 expression in hepatoma and in osteoarthritis, we therefore tested whether GBP5 had influence on the activation of Src and ERK1/2." (PMID 33608513, 2021).
Sepsis (4 papers, 2021 to 2025). Sepsis is defined as life-threatening organ dysfunction caused by a dysregulated host response to infection. "In sepsis‐associated liver injury, GBP5 overexpression aggravates liver damage by promoting the release of inflammatory cytokines through NLRP3 inflammasome activation." (PMID 40636987, 2025). "Moreover, overexpression of GBP5 in mice exacerbates LPS‐induced sepsis‐associated liver injury through activation of the NLRP3 inflammasome." (PMID 40636987, 2025). "In the GSE57065 control and sepsis groups, ATG5 (autophagy-related 5), and GBP5 (guanylate-binding protein 5) had degree 19 and 25, respectively." (PMID 33667236, 2021).
triple-negative breast carcinoma (4 papers, 2021 to 2025). An invasive breast carcinoma which is negative for expression of estrogen receptor (ER), progesterone receptor (PR), and human epidermal growth factor receptor 2 (HER2). "GBP5 emerges as a pan-cancer biomarker, with overexpression linked to immune checkpoint behavior and immunotherapy response across multiple tumor types, such as lung and triple-negative breast cancer." (PMID 40564939, 2025). "In triple-negative breast cancer, inhibiting GBP5 boosts PD-L1 efficacy, indicating its potential as a predictive marker for immunotherapy success." (PMID 40564939, 2025). "In tumors, it has been suggested that higher GBP5 mRNA expression levels can predict a good prognosis of triple-negative breast cancer, but the mechanism remains unclear." (PMID 36246628, 2022).